TSHZ1 (teashirt zinc finger homeobox 1)
Description:
Probable transcriptional regulator involved in developmental processes. May act as a transcriptional repressor (Potential).
Synonyms: SDCCAG33; TSH1; NY-CO-33; CAA
Tractability: PROTAC: ubiquitination databases record sites on it.
Gene: Protein-coding gene on chromosome 18 (75,210,755 to 75,289,950, forward strand). Ensembl gene ENSG00000179981.
Subcellular location: Nucleus
Subcellular location (Human Protein Atlas): Nucleoplasm
Gene Ontology:
Molecular function: DNA binding; DNA-binding transcription factor activity, RNA polymerase II-specific
Biological process: regulation of transcription by RNA polymerase II; regulation of gene expression
Cellular component: chromatin; nucleus
Genetic constraint (gnomAD): Loss-of-function variants: 12 observed, 67.18 expected, observed/expected ratio (o/e) 0.18, 90% interval 0.11 to 0.29. The upper end of that interval is the gene's LOEUF score, 0.29, which puts it in group 1 of 6, group 1 being the genes least tolerant of losing a copy. Missense variants: 1,302 observed, 1,462.7 expected, observed/expected ratio (o/e) 0.89, 90% interval 0.85 to 0.93. Synonymous variants: 632 observed, 646.76 expected, observed/expected ratio (o/e) 0.98, 90% interval 0.92 to 1.04.
Gene-disease validity (ClinGen):
ClinGen rates the evidence that TSHZ1 causes each of these diseases.
aural atresia, congenital (autosomal dominant): Limited.
Homologues: Orthologues: chimpanzee TSHZ1 (99% identical), macaque TSHZ1 (97% identical), mouse Tshz1 (93% identical), rat Tshz1 (92% identical), guinea pig TSHZ1 (92% identical), pig TSHZ1 (90% identical), dog TSHZ1 (89% identical), rabbit TSHZ1 (89% identical), tropical clawed frog tshz1 (82% identical), zebrafish tshz1 (69% identical), Drosophila melanogaster tio (16% identical), Drosophila melanogaster tsh (13% identical). Paralogues in human: TSHZ3 (58% identical), TSHZ2 (51% identical).
Diseases named in the same sentence as TSHZ1 in open-access papers:
TSHZ1 is named in the same sentence as 21 diseases in open-access papers, as found by Europe PMC text mining. Sharing a sentence is not in itself a finding about the gene and the disease. The quoted sentences say what the papers report.
Anosmia (2 papers, 2022 to 2024). An inability to perceive odors. "TSHZ1 is linked to congenital aural atresia and anosmia; Tshz1-/- leads to neonatal lethality in mouse experiments." (PMID 38764094, 2024). "We have identified a gene regulatory network, Gsx1/2 – Dlx1/2/5/6 – GAD2/1/Sp8/Sp9 – Tshz1 – Prokr2, which governs OBiN development; mutations of some of these genes result in human Kallmann syndrome with abnormal olfactory function (anosmia or hyposmia)." (PMID 34374948, 2022).
colon cancer (2 papers, 2011 to 2025). "Apparently Teashirt genes/proteins have never been associated to carcinogenesisexcept that TSHZ1 protein was found reactive with an autologous IgG from patientswith colon cancer (NY-CO-33 colon cancer antigen)." (PMID 21423795, 2011).
cleft lip (1 paper, 2022). Congenital defect in the upper lip where the maxillary prominence fails to merge with the merged medial nasal prominences. "The region related to cleft lip and cleft palate is 18q22.3q23, and the possible related pathogenic genes are SALL3 and TSHZ1." (PMID 36123715, 2022).
Insulin resistance (1 paper, 2021). Increased resistance towards insulin, that is, diminished effectiveness of insulin in reducing blood glucose levels. "The whole-body insulin resistance possibly promoted by ANKRD55 would endorse the insulin resistance stimulated by cytokines release from visceral fat and the impaired glucose-stimulated insulin secretion in pancreatic β cells mediated by the significant gene TSHZ1." (PMID 35058972, 2021).
Obesity (1 paper, 2022). Accumulation of substantial excess body fat. "TSHZ1 regulates pancreatic beta cell maturation and contributes to type 2 diabetes and obesity." (PMID 36389068, 2022).
ovarian carcinoma (1 paper, 2015). A malignant neoplasm originating from the surface ovarian epithelium. "In ovarian cancer cells, overexpression of Zeb1 induced mesenchymal markers TSHZ1 and FBN1, thus promoting EMT." (PMID 26356073, 2015). "Overexpression of Snail in ovarian cancer cells induced mesenchymal markers, such as tea-shirt zinc finger homeobox (TSHZ1), collagen type Vα, and fibrillin-1 (FBN-1), while suppressing E-cadherin, myosin-5C, keratin-18, keratin-8, annexin-A3, and suppressor of tumorigenicity 14 (ST14)." (PMID 26356073, 2015).
cancer (6 papers, 2011 to 2025). A tumor composed of atypical neoplastic, often pleomorphic cells that invade other tissues. "TSHZ1 encodes a colon cancer antigen in humans, and the encoded protein may be involved in the transcriptional regulation of developmental processes." (PMID 34290737, 2021). "Another polymorphism, rs12970291 near gene TSHZ1, was associated with both CRC and EC (OR = 1.26, P = 4.82 × 10−8), with the alleles showing opposite effects on the risks of the two cancers." (PMID 26621817, 2015). "The promoter regionof the TSHZ1 gene, which is expressed in both normal and cancer cells/tissues ofbreast and prostate, was found unmethylated irrespectively of the normal/cancerstatus." (PMID 21423795, 2011).
neoplastic diseases (3 papers, 2017 to 2023). "However, most studies thus far have focused on TSHZ3 25, with only sporadic reports available concerning TSHZ1 and TSHZ2 in non-neoplastic diseases." (PMID 33850468, 2021).
TSHZ1 also shares sentences with these, for which no sentence is quoted: endometrial cancer (2 papers); ameloblastoma (1); Cognitive impairment (1); colorectal cancer (1); epilepsy (1); heart failure (1); high blood pressure (1); Immunodeficiency (1); major depressive disorder (1); schizophrenia (1); Sepsis (1); thyroid cancer (1); type 2 diabetes (1).